SMARCB1 (SWI/SNF related BAF chromatin remodeling complex subunit B1)
Diseases named in the same sentence as SMARCB1 in open-access papers (continued):
Sharing a sentence is not in itself a finding about the gene and the disease.
tumor (continued). "Although our patient had a SMARCB1-deficient tumor in the parapharyngeal space, the progression was slow, and the prognosis after radiotherapy was favorable, indicating a rare course." (PMID 39398818, 2024). "FHD-609, another potent and selective heterobifunctional protein degrader of BRD9, was evaluated in patients with advanced SS or advanced SMARCB1-loss tumours in a Phase I clinical trial (NCT04965753)." (PMID 39796641, 2024). "The definitive diagnosis for ATRT relies on genetic/molecular analysis, specifically the loss of nuclear SMARCB1/INI1 or SMARCA4 expression in tumour cells." (PMID 38466393, 2024). "Further studies are necessary to investigate the effects of EZH2 inhibitors on the tumor microenvironment and their ability to enhance immunotherapy including immune checkpoint blockade in SMARCB1-deficient tumors." (PMID 39472584, 2024). "One of the first documented implications of remodelers in cancer was the identification of BAF as a tumor suppressor in rare malignant rhaboid tumor (MRT) caused by biallelic inactivation of BAF47 (hSNF5, INI1, and SMARCB1)." (PMID 38914477, 2024). "RMC and other SMARCB1‐deficient tumours have previously been shown to be particularly susceptible to proteotoxic stress." (PMID 37226898, 2023). "One study profiled 192 ATRT tumours and identified 3 tumours that showed retained SMARCB1 expression, with all 3 of these tumours carrying a mutation in SMARCA4 and clustering in the SHH-subgroup of ATRT." (PMID 37433987, 2023). "A comprehensive French study genetically profiled NF2 patient blood and tumor DNA and revealed additional mutations in SMARCB1 and LZTR1 in 65% of patients." (PMID 38058737, 2023). "Our findings show the benefit of methylation profiling of SMARCB1‐deficient tumours and in particular its value in separating MRT from EpS." (PMID 37316954, 2023). "Loss of SMARCB1 expression resulting from deletions/mutations has emerged as a defining diagnostic feature in various neoplasms in both children and adults." (PMID 37974295, 2023). "SMARCB1-deficient RMC is an aggressive tumor that commonly affects males and is predominantly right sided." (PMID 37367052, 2023). "The tumour was fully characterised in vivo, corresponding to a supratentorial AT/RT with nuclear loss of SMARCB1 protein and corresponding to methylation class AT/RT-SHH." (PMID 38001067, 2023). "Expression profiling of SMARCB1-deficient AT/RT tumours suggests these arise from stem cells; however, there is limited understanding of tumour progression." (PMID 37294080, 2023). "Given that RMC tumours are defined by loss of SMARCB1 and exhibit high levels of proteotoxic and replication stress." (PMID 37226898, 2023). "Here, we explored the methylation landscape and the immune microenvironment of EpS in the context of other SMARCB1‐deficient tumours, with the aim of identifying potential therapeutic targets." (PMID 37316954, 2023). "Additional immunostainings on the primary tumor showed partial loss of SMARCB1 and SMARCA2, and patches of nuclear β-catenin positivity." (PMID 38201285, 2023). "In the vast majority of cases, the genetic hallmark of these tumors is a pathogenic variant in the SMARCB1 tumor suppressor gene located on chromosome 22q, that codes for a subunit (INI1) of the SWI/SNF chromatin remodeling complex." (PMID 37416813, 2023). "It was previously thought that SMARCB1 was the exclusive recurrent mutation that characterised ATRT tumours, either through germline or somatic SMARCB1 mutations, or deletions on chromosome 22q." (PMID 37433987, 2023). "Heterozygous mutations cause rhabdoid tumor formation in 10–30% of mice, suggesting that SMARCB1 is a bonafide tumor suppressor." (PMID 37093326, 2023). "This led to treatment of SMARCB1‐deficient tumours with ICIs as monotherapy, dual therapy, or in combination with other anti‐tumour agents in clinical trials; these included patients with EpS, although the numbers were limited." (PMID 37316954, 2023).
tumor (continued). "Each primary tumor and related recurrence had the same mutations in SMARCB1 or SMARCA4 and genotype matching confirmed that they belonged to one patient based on the identification of common SNPs." (PMID 37450044, 2023). "SMARCA4-UT histologically resembles SMARCB1 (INI1)-deficient tumors, showing a highly rhabdoid appearance and frequent cytokeratin expression in tumor cells." (PMID 37115343, 2023). "For example, the biallelic loss of Smarcb1 in defined cell populations was described to cause embryonic lethality, rhabdoid tumours or cerebellar hypoplasia." (PMID 37219662, 2023). "Another phase I/II trial of a combination regimen (i.e., tazemetostat, the anti-PD-1 nivolumab, and the anti-CTLA-4 ipilimumab) in SMARCB1 or SMARCA4-deficient neoplasms has just been designed (NCT05407441)." (PMID 37213274, 2023). "SWI/SNF-related, matrix-associated, actin-dependent regulator of chromatin subfamily B member 1 (SMARCB1) is a SWI/SNF protein complex that was considered to be a tumor suppressor in past studies and plays an important regulatory role in the organism." (PMID 37367052, 2023). "Mutations affecting the SWI/SNF complex are documented in 20% of human SMARCB1-deficient neoplasms, which affect patients of a wide age range, from infants to elderly patients in their ninth decades." (PMID 35804041, 2022). "In this study, we molecularly and immunophenotypically characterized nine SMARCB1 (INI1) deficient intrathoracic neoplasms and correlated this information with clinical presentation and outcome." (PMID 35864317, 2022). "These different tumor types display highly variable immunophenotypes with SMARCB1-deficient carcinomas showing variable squamous immunophenotype, while their SMARCA4-related counterparts lack such features altogether." (PMID 35307773, 2022). "Further work is needed to understand how loss of SMARCB1 drives tumor formation in ES and RMC as compared to rhabdoid tumors." (PMID 35892904, 2022). "Loss of function in SMARCB1/INI1 has been observed in a group of malignancies collectively defined as SMARCB1/INI1-deficient neoplasms." (PMID 35804041, 2022). "SMARCB1 deficiency has been described in carcinomas of the gastro-entero-pancreatic tract, the head and neck region and in neoplasms of the genitourinary tract, representing a broad histomorphologic spectrum and polyphenotypic variations." (PMID 35864317, 2022). "We investigated if these intrathoracic SMARCB1 - deficient neoplasms represent an own unique entity." (PMID 35864317, 2022). "We propose a model, wherein Smarcb1 loss in PGCs leads to a reversal of germ cell specification and misguidance to various body locations and, ultimately, to tumor formation." (PMID 35318328, 2022). "Much less is known about SMARCB1 (INI1) deficient intrathoracic neoplasms, which are rare, often misclassified and understudied." (PMID 35864317, 2022). "Given the lack of druggable targets and the high mortality associated with SMARCB1-deficient tumors, a significant research effort has been directed toward understanding the mechanisms of tumor transformation and proliferation." (PMID 35892904, 2022). "SMARCB1 (INI1) deficient carcinoma is a rare tumor that develops over a wide age range (median 52 years) with a slight predilection for male patients." (PMID 35326613, 2022). "Tazemetostat, an EZH2 inhibitor, is currently under evaluation in different Phase I and II clinical trials in tumours with SMARCB1, SMARCA4 and EZH2 mutations with positive results in patients with different solid tumours." (PMID 36138075, 2022). "Only two somatic mutations were identified in the tumor DNA: a loss of function in the SMARCB1 gene, c.769C > T; p.(Gln257Ter), with a variant allelic frequency (VAF) of 96.3%, and a missense-damaging mutation in PTEN (c.510T > G; p.(Ser170Arg), VAF = 93.6%)." (PMID 35200537, 2022).
tumor (continued). "Due to this increased risk, we have recommended that a changing tumour, in someone with SMARCB1 germline pathogenic variant, especially one causing functional impairment, should prompt exclusion of malignant transformation." (PMID 35361920, 2022). "In the future, it will be important to perform fate-mapping experiments to study the migration route of Smarcb1-mutated PGCs and to clarify the reasons for the long latency of tumor formation in mice." (PMID 35318328, 2022). "In this study, we analyzed the methylome of seven RMC samples and compared them to the methylation data of other SMARCB1 deficient tumor entities." (PMID 36291828, 2022). "Other than this unique case of germ line mutant allele LOH, the genomic landscape of the RMC tumor was generally representative of disease, including biallelic inactivation of SMARCB1 with a low mutational burden otherwise." (PMID 35837094, 2022). "The investigation of an INI1 (SMARCB1) deficient neoplasm is highly recommended in such cases when BRG1 (SMARCA4) is retained." (PMID 35864317, 2022). "This trend is likely to continue as more SMARCB1-deficient tumor samples are sequenced and analyzed, hopefully leading to more targeted therapies that are suited for each molecular subtype." (PMID 35892904, 2022). "Mutations in the SMARCB1 (22q11.23) or LZTR1 (22q11.21) tumor-suppressor genes are present in most patients; however, they are insufficient to cause schwannomatosis and require additional somatic mutations." (PMID 35291225, 2022). "A similar but focused orthogonal screen revealed that proteasomal inhibition reduces tumor cell growth of SMARCB1-deficient cancers in vitro and increases survival in vivo." (PMID 35892904, 2022). "The histological examination demonstrated an atypical teratoid/rhabdoid tumor with SMARCB1/INI1 loss." (PMID 35433419, 2022). "There are very limited data on the tumors classified as CRINET, and loss of SMARCB1 (INI1/BAF47) has been reported as characteristic of this tumor type." (PMID 35969220, 2022). "Due to the relatively low number of currently sequenced patient tumor samples with SMARCB1 mutations, it is difficult to identify the pathogenic variants due to low signal." (PMID 35892904, 2022). "For this reason, further work is needed to understand how SMARCB1-deficient cancers respond to immunotherapy, especially when used in combination with other anti-tumor agents." (PMID 35892904, 2022). "Analysis of copy number variants (CNVs) revealed a biallelic loss of SMARCB1 in tumour and both nerve roots, which again we were able to validate through INI1 staining." (PMID 33658498, 2021). "Subsequently, we assessed the tumor samples for mutations outside of SMARCB1 and integrated RNA sequencing to interrogate the structural variants at the SMARCB1 locus." (PMID 34261517, 2021). "As expected, SMARCA4 expression levels were reduced, whereas SMARCB1 expression levels were higher in SMARCA4-deficient tumor samples compared to all other ATRT subgroups (online resource)." (PMID 33331994, 2021). "The sensitivity of MMA and EC8042 was superior to traditional DNA damaging agents and linked to the causative mutation of the tumor, SMARCB1 deletion." (PMID 33332735, 2021). "A complete loss of SMARCB1 expression in tumor cells can be the result of a second-hit or an alternative inactivating mechanism, such as methylation pattern, variants in non-coding regions, promoters or enhancers." (PMID 34777208, 2021). "HDACs are frequently overexpressed in SMARCB1-mutant tumours and in ARID1A-deficienct cancers, making them sensitive to HDAC inhibitors." (PMID 33941852, 2021). "In each of these, immunohistochemistry for SMARCB1 is a reliable surrogate for underlying SMARCB1 inactivation, since tumor cell nuclei frequently show loss of expression alongside retained expression in non-neoplastic cells." (PMID 33921435, 2021).
tumor (continued). "The exact mechanism linking renal medullary hypoxia to tumorigenesis, and loss of the SMARCB1 tumor suppressor in particular, remains to be determined." (PMID 34885132, 2021). "In patient 1’s tumour, we detected apparent biallelic loss of SMARCB1 as a result of an inverted translocation between SMARCB1 intron 3 and a non-coding region on chromosome 5 (hg19 chr22:24138567–chr5:176754524)." (PMID 34931022, 2021). "The study cohort consisted of 56 SWI/SNF‐deficient DDEC/UEC (2 POLE‐mutated), which showed either SMARCA4 (BRG1) loss, ARID1A/1B co‐loss, or SMARCB1 (INI1) loss in the undifferentiated tumor, and 26 SWI/SNF‐intact DDEC/UEC (4 POLE‐mutated)." (PMID 33125840, 2021). "These tumors present the lowest mutational burden of any human tumor sequenced to date, suggesting that tumorigenesis in MRTs is induced by the epigenetic misregulation consequence of SMARCB1 loss." (PMID 32071317, 2020). "The constellation of findings in tumor and peripheral blood sequencing suggested the possibility of germline single copy SMARCB1 loss, followed by somatic loss of the remaining SMARCB1 allele due to copy neutral loss-of-heterozygosity." (PMID 33344321, 2020). "The unveiled role of SWINGN in the establishment of its regulatory network provides an epigenetic signature for tumor progression linked to SMARCB1 alterations." (PMID 32071317, 2020). "Neither of the primary tumor lines developed in this study were capable of producing tumor xenografts and so this study relied on utilizing the SMARCB1‐deficient rhabdoid cell line G401 as a substitute for an actual RMC cell line in its in vivo studies." (PMID 32259323, 2020). "The genetic analysis of other patients showed heterozygous c.175C>T mutation in exon 2 of SMARCB1 in the tumor's DNA." (PMID 32328470, 2020). "Further mechanistic research showed that the expression level of the tumor suppressor gene p16INK4a is downregulated in SMARCB1/SNF5-deficient tumor cells and increased in EZH2-deficient cells." (PMID 31590683, 2019). "In one WHO°II and its corresponding recurrent tumor, the already known driver mutation SMARCB1 R377H was detected." (PMID 31470906, 2019). "In this patient with a SMARCB1 mutation in exon 9, inactivation of the second allele had occurred in the tumor tissue." (PMID 31273213, 2019). "SMARCB1 is also a potent tumor suppressor, being mutated or deleted in nearly all atypical rhabdoid/teratoid tumors (AT/RTs), aggressive cancers that primarily affect the central nervous system and which can be diagnosed at very young ages, even prenatally." (PMID 31033435, 2019). "It was also found that SMARCB1/SNF5-deficient tumor cells are highly sensitive to EZH2 inhibitors, which significantly inhibit cell proliferation and increase apoptosis." (PMID 31590683, 2019). "The risk of RT development seems to be time‐dependent in the sense that a specific developmental time window exists during which the tumor progenitor cell is vulnerable to complete SMARCB1 protein loss initiating RT growth." (PMID 29779243, 2018). "Unlike the GIST and gastric cell lines used in the previous studies, the A204 rhabdoid tumour cell line has a very simple genome where the loss of the SWI/SNF chromatin remodelling subunit SMARCB1 is the only known cancer-associated driver." (PMID 28842319, 2018). "These mutations almost always lead to loss of their encoded protein (SMARCA4 or SMARCB1) by immunohistochemistry, making this an important diagnostic marker for these tumours." (PMID 27866340, 2017). "In other types of tumour cell, however, the loss of the SMARCB1 wild-type allele leads to complete loss of protein expression." (PMID 27921248, 2017). "The third step is the somatic mutation of the remaining NF2 allele located on the chromosome harbouring the germline SMARCB1 mutation which is retained in the tumour." (PMID 27921248, 2017).
tumor (continued). "In eight tumours from patients with germline SMARCB1 mutations, LOH of 22q was found to be caused exclusively by whole chromosome loss or large deletions within 22q, but not by mitotic recombination." (PMID 27921248, 2017). "Of note, one deleterious frameshift mutation affecting ARID1A exon 1 was found in one tumor in addition to SMARCB1 loss." (PMID 28427232, 2017). "Although the ovarian type of RT (SCCOHT) is almost always caused by mutations in SMARCA4, and extra-ovarian RT by mutations in SMARCB1, it is possible for multiple tumour types within the rhabdoid tumour spectrum to be caused by the same mutation." (PMID 27866340, 2017). "MRTs are characterized by biallelic alteration of the SMARCB1/INI1/SNF5/BAF47 tumor-suppressor gene, which encodes a core component of the chromatin-remodeling complex SWI/SNF." (PMID 28521298, 2017). "Altogether, clinical outcome was available for 16 patients with an adult-onset (>15 years at diagnosis) SMARCB1-deficient tumor, including 6 RT and 10 SD-NRT." (PMID 28427232, 2017). "Whole genome and transcriptome sequencing on seven tumor specimens and three cell lines confirmed SMARCB1 loss by variable mechanisms, but revealed a complex genome with an unexpectedly high mutational rate for a tumor of younger patients." (PMID 27732970, 2017). "As expected, all tumours showed a complete loss of Smarcb1 expression, while vehicle-treated brains showed a homogenously positive staining." (PMID 26818002, 2016). "In this study we use a high throughput phosphoproteomic analysis comparing Smarcb1 deficient and proficient tumor cells to further identify aberrant signaling associated with Smarcb1 deficiency." (PMID 26370283, 2015). "The malignant rhaddoid tumor G401 cells harbor homozygous inactivating mutations in SMARCB1/INI1 that render them depend on WT EZH2 activity for survival." (PMID 26360609, 2015). "Western blot analysis for an additional auto-phosphorylation site of the EGFR, residue Y1092, showed higher levels of phosphorylation in Smarcb1 deficient tumor cells compared with Smarcb1 proficient cells under low serum." (PMID 26370283, 2015). "Inhibition of EGFR signaling with Gefitinib or Lapatinib reduced proliferation of Smarcb1 deficient tumor cells as demonstrated by a WST1 proliferation assay." (PMID 26370283, 2015). "By comparing Smarcb1 deficient tumor cells with their Smarcb1 proficient counterparts we identified persistent activation of AKT in Smarcb1 deficient cells, which plays a key role in the survival and proliferation of these tumor cells." (PMID 26370283, 2015). "The most widely known tumor suppressor and diagnostic biomarker for AT/RT is INI1 (also known as SMARCB1, hSNF5, BAF47)." (PMID 26109171, 2015). "Although the basis for this paradoxical response of EGFR to Gefitinib is unclear, both inhibitors caused reduction of AKT phosphorylation, indicating that the ErbB pathway is responsible for the persistent activation of AKT in Smarcb1 deficient tumor cells." (PMID 26370283, 2015). "We previously identified persistent activation of AKT in Rhabdoid tumor cells which was Smarcb1 dependent and central for proliferation and survival of Smarcb1 deficient tumor cells." (PMID 26370283, 2015). "DNA copy number profiling has also shown that often there is only a single gross genomic aberration present in almost all tumours, which is loss of chromosome 22, where SMARCB1 is located." (PMID 26998479, 2015). "The triple - SILAC (Stable Isotopic Labeling of Amino Acids in Cell Culture) protocol was used to compare Smarcb1 deficient and proficient tumor cells (Cell line 365 containing an empty retroviral vector as control (pMIG) or pMIG-Smarcb1 respectively)." (PMID 26370283, 2015). "To address the origin of EGFR activation in Smarcb1 deficient tumor cells we considered various mechanisms that can cause aberrant activation of EGFR and downstream signaling." (PMID 26370283, 2015).